FGF21 (fibroblast growth factor 21)
Diseases named in the same sentence as FGF21 in open-access papers (continued):
Sharing a sentence is not in itself a finding about the gene and the disease.
cancer (continued). "TWIST2 can suppress the expression of FGF21 to activate the AMPK/mTOR signalling pathway which inhibits the progression of various cancers." (PMID 36118870, 2022). "As a stress-responsive hepatokine, the implications of FGF21 in cancers have been focused on in recent years." (PMID 36263162, 2022). "Another plausible reason for FGF21 participating in cancers is its high sensitivity to macronutrients." (PMID 36263162, 2022). "Our results are similar to those of a previous report describing the role of FGF19 (another hormone-like FGF similar to FGF21) in a cancer model." (PMID 31408968, 2019). "Western blot analyses revealed that all receptors for FGF21 were expressed in all cancer cells and normal cells." (PMID 31408968, 2019). "Inspite of the fact that ccRCC is a rare type of cancer; our limited number of cases and controls, allowed us to demonstrate that FGF21 levels were significantly increased in ccRCC patients compared with HC." (PMID 27358750, 2016). "The molecular link between plasma Fgf21 and IHTG levels was associated with dysregulation of both metabolic and cancer-related pathways." (PMID 27470139, 2016). "Perhaps the PPARα‐FGF21 axis could be further explored in cancer metabolism, given that the role of FGF21 within cancer metabolic rewiring is understudied." (PMID 41131959, 2026). "This may open an interesting avenue of research for FGF21 within cancer as lipidomic remodeling is well characterized within tumors, leaving cancer cells reliant on fatty acid oxidation for energy production." (PMID 41131959, 2026). "Until recently, the role of FGF21 in cancer immunity remained unexplored." (PMID 40242310, 2025). "However, recent findings suggested that FGF21 has a crucial role in suppressing cancer immune responses." (PMID 40242310, 2025). "These therapies target specific molecules, including proteins involved in FGF receptor (FGFR)-mediated signalling and cancer immunity, and could affect the prognosis of patients with high serum FGF21 levels." (PMID 40242310, 2025). "We previously discussed the potential role of FGF21 in cancers." (PMID 38238320, 2024). "Much attention has been paid to the roles of GDF15 and FGF21 in cancers." (PMID 36642986, 2023). "Also, serum FGF21 level was higher in patients with endometrioid carcinoma, sufficing it to diagnose the cancer stage and grade 114." (PMID 36263162, 2022). "Previous studies considered FGF21 had less risk of cancer induction since it is the only family member without mitogenic action." (PMID 36618930, 2022). "Furthermore, FGF21 promotes cancer progression via the upregulation and induction of the FGFR signaling axis, including AKT and ERK phosphorylation." (PMID 36077709, 2022). "However, aberrant expression of FGF21 has been found related to cancer development, and it is suggested as a promising cancer biomarker." (PMID 36618930, 2022). "Instead, FGF21 may be an ideal non-invasive biomarker applied in regular health tests for discovering and preventing cancers at an early stage, though the sensitivity and cancer-specificity for clinical use need to be evaluated critically." (PMID 36263162, 2022). "In particular, FGF21 is a known regulator of energy metabolism, and high serum levels of FGF21 have been found in age-related cachexia patients, suggesting a potential role for FGF21 in cancer cachexia." (PMID 35319749, 2022). "Focusing on FGF21, the findings discussed in this review indicated its high sensitivity to adaptive stress response, its important role in modulating liver-participated inter-organ crosstalk, and its potential value in cancer diagnosis and treatment." (PMID 36263162, 2022). "Such limited understanding of the role of FGF21 and detailed mechanism in cancer development may provide new avenues for future research." (PMID 34572066, 2021). "Correlation of serum FGF21 in cancer-induced cachexia requires further investigation." (PMID 33925872, 2021).
cancer (continued). "Few population-based studies have been conducted to investigate the role of FGF-21 in cancer." (PMID 30425347, 2018). "Finally, within the list of upregulated genes in the UCHL1 KD we also found several cancer-associated genes such as SERPINB4, FGF21, NUPR1, SBSN, GDF1, HMOX1, or SOCS2, which suggested the activation of potential compensatory mechanisms in these KDs cells." (PMID 28472177, 2017). "It is noteworthy that all of the cancer deaths occurred in the high-FGF21 group." (PMID 28582462, 2017). "Even though FGF19, FGF21 and FGF23 are all endocrine factors, based on the effects of FGF21 on fuel energy, oxidative stress, life-span and its pleiotropic metabolic actions; investigators have suggested that FGF21 is a very promising molecule with therapeutic potential to combat cancer." (PMID 27358750, 2016). "Tumor‐secreted FGF21 may also regulate cancer cell metabolism in an autocrine manner." (PMID 41131959, 2026). "Interestingly, cancer increased plasma FGF21 levels, and this increase was enhanced upon TN." (PMID 40237521, 2025). "Thus, FGF21 not only holds promise as a potential biomarker for MASLD but may also serve as a therapeutic target for cancers like HCC." (PMID 41262444, 2025). "Recently, it was reported that secreted FGF21 may influence cancer immunity." (PMID 40242310, 2025). "Thus, it can be speculated that elevated systemic FGF-21 levels may contribute to the increased inflammation seen in cancer cachexia." (PMID 37755304, 2023). "In addition, String pathway interaction analysis identified six proteins (TGFBR2, TGFA, FGF21, SMAD4, TGFBR1, and FZD3) that were at the intersection of the cancer-associated pathways and, importantly, which were restored to their younger crosstalks by the rounds of TPE." (PMID 35999337, 2022). "Furthermore, it may lead to the effects of FGF21 on cancer cells easily overshadowed by its outstanding regulation ability of glucose metabolism, which the author also mentioned." (PMID 36263162, 2022). "However, up to date, little is known about the role of FGF21 in cancer initiation and progression." (PMID 27358750, 2016). "Consequently, the suppressive effect of FGF21 on cancer immunity could lead to a poorer prognosis." (PMID 40242310, 2025). "In this study, other cytokines of importance to cancer that were upregulated upon the use of cannabigerol included IL-28A, CCL22, FGF-21, and IL-33." (PMID 36923728, 2022). "The biomarkers most significantly associated with short-term mortality were IL-6, IL-10, IL-8, MCP-1 (mainly inflammatory markers), FGF-21, ST1A1, 4E-BP1 and CST5 (classified by OLINK as cardiovascular markers) and FGF-23 (classified as a cancer marker)." (PMID 36209229, 2022). "Fibroblast growth factor 21 (FGF21) plays an important role in regulating glucose and lipid metabolism, but its role in cancer is less well-studied." (PMID 33753729, 2021). "Even less is known on the role of circulating levels of FGF21, FGF19 or FGF23 as a cancer biomarker." (PMID 27358750, 2016). "Emerging data suggest that GLP-1 and its downstream mediators, including fibroblast growth factor-21 (FGF-21), could have significant roles in cancer development and progression." (PMID 39777709, 2025). "Therefore, FGF21 may be considered as a promising biomarker to predict cancer progression, and targeting FGFR may represent a new therapeutic approach for PTC patients with high FGF21 serum levels." (PMID 36077709, 2022). "Considering the information discussed, it is highly possible that FGF21 could be a universal cancer biomarker rather than a specific diagnosis biomarker for ccRCC, and it should be used in combination with other existing biomarkers." (PMID 27358750, 2016). "In recent decades, the MR diet has been widely recommended because of its health benefits, such as repressing cancer growth, improving cancer therapy, increasing the longevity of some species, and protecting against the negative effects of aging on metabolic syndrome via an FGF21 mechanism." (PMID 36145081, 2022).
heart diseases (18 papers, 2010 to 2025). "Fibroblast growth factor 21 is considered a regulator in maintaining energy homeostasis and shows a positive role in preventing damage caused by cardiac diseases." (PMID 37416922, 2023). "In the next section, we will use FGF21 as an example to investigate the role of UPRmt-regulated mitokines in cardiac diseases." (PMID 41234361, 2025). "Proteins such as CDCP1, CXCL17, FGF21, GDF15, and IGFBP4 commonly mediated effects in both the Air and Noise Pollution and Social Deprivation groups, while GDF15 was notably linked to heart disease across these patterns." (PMID 41290610, 2025). "Several studies have consistently reported an elevation of FGF21 in various conditions, including heart disease and metabolic disorders." (PMID 38789571, 2024). "The review mainly expounds on the possibility that FGF21, as a promising cardioprotective factor, improves cardiac function and ultimately retarding the progress of cardiac diseases." (PMID 37416922, 2023). "The FGF21 analog shows promise as a candidate for the diagnosis and therapy of cardiac diseases, but further investigation is needed to support its use in the future." (PMID 37416922, 2023). "Fibroblast growth factor 21 (FGF21) is a relatively novel polypeptide ligand that has been shown to exert cardioprotective effects in various forms of heart diseases." (PMID 37484982, 2023). "As patient with heart diseases always has metabolic dysregulation problems, high serum FGF21 levels in these patients are reasonable." (PMID 36180826, 2022). "Despite intensive study of the metabolic functions of FGF21, its important role in heart disease needs further exploration." (PMID 30157856, 2018). "Fibroblast growth factor-21 (FGF21) is a mediator of the mitochondrial pathways and has a relevant role in heart diseases." (PMID 27690014, 2016). "While numerous data have been published in animal model, little is known about FGF-21 in human subjects, particularly for patients with heart diseases." (PMID 21206918, 2010). "Furthermore, FGF21 is induced in failing human hearts but human trials with FGF-21 have not yet been performed to actually demonstrate the protective role of FGF21 in heart diseases." (PMID 27690014, 2016). "Collectively, these studies suggest that FGF21 is a potential new biomarker for cardiac diseases." (PMID 26379627, 2015). "Moreover, while studies exploring the direct role of FGF21 in driving cardiac functional changes in NAFLD are limited, increased levels of circulating FGF21 have been observed in several cardiac diseases and have been associated with diastolic dysfunction in both humans and mice." (PMID 38519536, 2024). "In heart diseases, serum FGF15/19 levels or FGF21 and FGF23 levels decrease or increase, respectively, indicating their possible roles in heart pathophysiology." (PMID 27803896, 2016). "Serum FGF15/19 levels are decreased and FGF21 and FGF23 levels are increased in heart diseases, which also suggests their roles in heart pathophysiology." (PMID 27803896, 2016). "Signaling disorders of FGF2, FGF21, and FGF23 as paracrine signals also result in heart diseases." (PMID 27803896, 2016). "In addition, heart diseases affect serum levels of FGF15/19, FGF21, and FGF23, indicating that these FGFs are serum biomarkers for heart diseases." (PMID 27803896, 2016). "The increase in FGF21 secretion and the improvement of fatty acid metabolism may be crucial for the novel liver-cardiac crosstalk mechanism, which may shed light on the prevention and treatment of AMI and related heart diseases." (PMID 34368135, 2021).
myopathy (17 papers, 2014 to 2024). A disease of the muscle in which the muscle fibers do not function properly. "FGF21 can also be detected in myopathy caused by various mitochondrial abnormalities, including mitochondrial translation failure, mitochondrial DNA deletion, and impaired respiratory chain conduction." (PMID 38069273, 2023). "In myocytes isolated from myopathy patients with an iron-sulfur cluster deficiency, elevated FGF21 expression and secretion correlate with increased expression of ketogenic enzymes." (PMID 33381084, 2020). "FGF-21 was shown to increase in mitochondrial dysfunction and myopathy secondary to iron-sulphur cluster deficiency." (PMID 28825656, 2017). "For example, the level of fibroblast growth factor 21 (FGF21) is a possible biomarker for mitochondrial-based myopathy." (PMID 39323625, 2024). "Irisin, BDNF, FGF-21, and probably osteonectin are the most promising biomarkers of HF-related myopathy and cachexia, while their role in the prediction of adverse cardiac remodeling and poor outcomes requires to be elucidated in the future." (PMID 33520013, 2021). "FGF21 was shown to be increased in sera of humans with mtDNA‐related myopathies." (PMID 29427317, 2018). "We found increased transcript levels of Fgf21 in COX10 KO muscle and chronically elevated levels of circulating FGF21 protein commencing from the earliest stage of myopathy (9‐, 4‐, and 5‐fold at 50, 100, and 200 days, respectively)." (PMID 37222423, 2023). "Working from the assumption that skeletal muscle is a primary source, FGF-21 may only be a useful mitochondrial endpoint for patients with myopathies as normal levels have been observed in MD that do not manifest as myopathy." (PMID 37144479, 2023). "That myopathy was not a major feature was supported by our FGF-21 results: FGF-21 levels were also lower in the group of patients with nuclear gene mutations than it could be expected, but similar to those reported earlier in ataxic POLG patients." (PMID 33501425, 2021). "Since FGF-21 is mainly produced in the skeletal muscle, a main disadvantage of FGF-21 as a biomarker of MIDs is that it may not be useful in MID patients without myopathy." (PMID 29385732, 2018). "The mean circulating concentration of GDF-15 was almost identical in healthy children (mean = 350.3, SEM = 21 pg/mL) and in myopathic non-mitochondrial controls (349.1 pg/mL) whereas FGF-21 was higher in children with myopathy (136.1 pg/mL) than in unaffected controls (77.6 pg/mL)." (PMID 26867126, 2016). "We have no biomarkers (FGF-21 and GDF-15) follow-up data; their role in future trials is still unclear, although in TK2 myopathy a reduction in GDF-15 levels after treatment has recently been observed." (PMID 35980466, 2022).
infection (16 papers, 2012 to 2025). The state of being infected such as from the introduction of a foreign agent such as serum, vaccine, antigenic substance or organism. "In this report, we show that FGF21 is induced by infection with influenza virus in both humans and mice." (PMID 40996795, 2025). "RT-qPCR analysis confirmed that both mRNAs were upregulated in a virus titer-dependent manner, with FGF21 showing a particularly pronounced increase, exceeding 100-fold over uninfected cells at 72 h post-infection." (PMID 39211324, 2024). "This, however, may be in favor of a hierarchical theory of insults so that, as the infection clears out, FGF-21 reflects an improvement in viral steatosis firstly, and only afterwards an improvement in metabolic steatosis." (PMID 37999215, 2023). "HIV exposure or infection may itself directly affect mitokine levels, as described for FGF21, and therefore the reasoning for other factors correlating with mitokine levels need to be carefully considered within the CPHIV population." (PMID 34972147, 2021). "Finally, Ad-ChREBP infection increased white adipose tissue Ucp1 mRNA levels with increased plasma Fgf21 levels." (PMID 30405056, 2018). "These negative effects were significantly amplified in FGF21 knockout mice but were entirely reversed by infection with aav-FGF21, showing that FGF21 can inhibit HP and ameliorate HP-mediated vascular damage." (PMID 37424900, 2023). "Mice lacking FGF21 had decreased food intake, body weight, and body temperature compared to wild-type mice following influenza virus inoculation, indicating reduced tolerance to the infection." (PMID 40996795, 2025). "Other factors, such as infection and intestinal injury, may also influence FGF21 and the present study may not provide sufficient discrimination to detect these associations." (PMID 31093598, 2019).